GSDMD (gasdermin D)
Diseases named in the same sentence as GSDMD in open-access papers (continued):
Sharing a sentence is not in itself a finding about the gene and the disease.
Sepsis (continued). "By employing genetic and pharmacological methods, targeting the pyroptosis pathway can effectively reduce the expression and function of NLRP3 and GSDMD in sepsis-AKI." (PMID 34926535, 2021). "On the molecular level, we demonstrated that antifungal therapy aggravated endotoxin sepsis through promoting Gasdermin D cleavage in the distal small intestine." (PMID 34707775, 2021). "GPX4 knockout activated the lipid peroxidation-dependent caspase-11, which triggered the GSDMD cleavage to induce pyroptosis during polymicrobial sepsis." (PMID 34820376, 2021). "As gasdermin‐induced pore formation plays a pivotal role in sepsis and numerous autoinflammatory diseases, there is increasing interest to develop small molecule inhibitors targeting GSDMD and other gasdermin family members." (PMID 33033617, 2020). "We have previously demonstrated that hepatocytes release HMGB1 in sepsis and that this requires caspase-11 and GsdmD." (PMID 32328059, 2020). "Emerging evidence suggests that GSDMD‐dependent pyroptosis induced by caspase‐1/11 inflammasome activation drives sepsis downstream of LPS exposure/TMEM173 activation/lipid peroxidation." (PMID 33033617, 2020). "Caspase-1-mediated GSDMD cleavage was consequently decreased, which prevented pyroptosis in LPS-induced sepsis in mice." (PMID 31189875, 2019). "Further, they also demonstrated that both Gsdmd−/− and Casp11−/− mice survived from LPS with lethal doses, authenticating the role of GSDMD in pyroptosis-triggered lethal sepsis and septic shock." (PMID 29706799, 2018). "On the other hand, blockade of pyroptosis by caspase-1/-11 or gasdermin D gene deletion renders mice resistant to endotoxin-induced sepsis, suggesting NLRP3 and other inflammasome activation play a critical role in sepsis." (PMID 29375379, 2017). "Sepsis, a life‐threatening dysregulated host response to infection, is frequently exacerbated by pyroptosis—a programmed, proinflammatory cell death process mediated by Gasdermin D (GSDMD) activation." (PMID 41536519, 2026). "GSDMD‐mediated pyroptosis plays a critical role in sepsis pathogenesis." (PMID 41536519, 2026). "In addition, phospholipase D2 (PLD2) deletion ameliorates sepsis-induced cardiomyopathy by suppressing cardiomyocyte pyroptosis via the NLRP3/caspase-1/GSDMD pathway." (PMID 40708650, 2025). "Experimental models have demonstrated that genetic ablation of inflammasome components—such as NLRP3, caspase-1, caspase-11, or GSDMD—confers protection against sepsis-induced mortality by attenuating systemic inflammation, coagulopathy, and multiorgan dysfunction." (PMID 40558557, 2025). "In this study, for the first time in the specific context of SIC, we demonstrate that sepsis patients with SIC show significantly elevated plasma levels of GSDMD - NETs signature proteins (N - GSDMD and MPO - DNA), and these elevations independently correlate with the risk of SIC." (PMID 40766307, 2025). "Endothelial GSDMD contributes to vascular injury and death in sepsis." (PMID 39927458, 2025). "Hepatocyte GSDMD regulates vascular injury through the release of HMGB1 in sepsis." (PMID 39927458, 2025). "However, in contrast to the results of GSDMD−/− mice, the survival rate of GSDMDhep‐/− mice was surprisingly lower in the LPS‐induced sepsis model." (PMID 40856013, 2025). "The 3 main mechanisms of endothelial pyroptosis in sepsis include the GSDMD-NT (gasdermin D N-terminal domain)-dependent pathway, the NLRP3 (nucleotide-binding domain, leucine-rich-containing family, pyrin domain-containing-3)-dependent pathway, and intercellular communication." (PMID 41280722, 2025). "We also identified the protective role of a GSDMD activation inhibitor during sepsis." (PMID 39927458, 2025). "Strategically, inhibiting key palmitoylation-related processes involved in GSDMD-induced macrophages pyroptosis and IL-1β release could attenuate sepsis-induced organ injury." (PMID 40461967, 2025).
Sepsis (continued). "GSDMD-NETs axis marker and outcomes in sepsis patients in different groups." (PMID 40766307, 2025). "Our research results demonstrate that ECG alleviates sepsis-induced ALI by inhibiting the NLRP3/Caspase-1/GSDMD signaling pathway-mediated pyroptosis, the Bcl-2/Bax/Caspase-3 signaling pathway-mediated apoptosis, and regulating the ZBP1/MLKL/RIPK1 signaling pathway-mediated necroptosis." (PMID 41496909, 2025). "Therefore, in this study, we constructed hepatocyte‐specific GSDMD knockout mice (GSDMDhep‐/−) and control mice (GSDMDflox+/+) to reveal the role of hepatic GSDMD in sepsis." (PMID 40856013, 2025). "Mice treated with LPS and nigericin showed rapid platelet swelling and membrane rupture, but these effects were absent in GSDMD-deficient platelets, suggesting the important role of platelet pyroptosis in sepsis." (PMID 40710328, 2025). "Notably, pharmacological inhibition of GSDMD shows considerable therapeutic potential in the management of sepsis." (PMID 41284375, 2025). "Additionally, inhibiting endothelial GSDMD activation via a polypeptide inhibitor alleviated endothelial damage and improved survival in a mouse model of endotoxemia or sepsis." (PMID 39927458, 2025). "Furthermore, GSDMD is involved in various diseases, including sepsis and neuroinflammatory conditions, via the STING signaling pathway." (PMID 40666504, 2025). "The ALT/AST analysis also proved that hepatic GSDMD deficient did not affect the dysfunction of liver in sepsis." (PMID 40856013, 2025). "Targeting GSDMD can serve as a novel therapeutic strategy for sepsis." (PMID 40783818, 2025). "Importantly, our observation aligns with the recent findings demonstrating that brain endothelial GSDMD activation mediates BBB breakdown during LPS-induced sepsis." (PMID 40821830, 2025). "Therefore, inhibiting endothelial GSDMD expression and activation decreased vascular injury and improved survival in mice with endotoxemia or sepsis." (PMID 39927458, 2025). "This study proposes for the first time that hepatic GSDMD plays a key protective role in sepsis." (PMID 40856013, 2025). "The HMGB1/RAGE signaling pathway regulates vascular injury through endothelial GSDMD in sepsis." (PMID 39927458, 2025). "Specifically, the O-GlcNAcylation of GSDMD is linked to the modulation of pyroptosis, suggesting that enhancing O-GlcNAcylation of GSDMD could be crucial for improving hypoperfusion in sepsis." (PMID 39742284, 2024). "Neutrophils may be involved in sepsis through the mechanisms dependent on GSDMD but unrelated to NETs." (PMID 38584157, 2024). "Furthermore, PSP significantly inhibited the expression of GSDMD-NT and reversed the increase in the mRNA expression levels of NLRP3/GSDMD signaling components in liver tissues, which has a protective effect on acute liver injury in sepsis." (PMID 39202931, 2024). "We further discovered that PBMCs from patients with sepsis showed considerably higher levels of cleaved GSDMD-positive cells than those from the healthy group, which is consistent with the fact that the cleavage of GSDMD enhances the creation of membrane pores during pyroptosis." (PMID 38169584, 2024). "Moreover, we also found that rh PLTP treatment inhibited the activation of the NLRP3 inflammasome/GSDMD signaling pathway in the heart tissue of mice with sepsis." (PMID 38584827, 2024). "GSDMD is regarded as a novel and ideal target for drug development in sepsis." (PMID 39267971, 2024). "GSDMD plays a pivotal role in the coagulation process during sepsis." (PMID 39445002, 2024). "In addition, the positive feedback mechanism between the RIPK3/MLKL and GSDMD pathways and inflammation promotes the development of sepsis." (PMID 38684668, 2024). "Targeting GSDMD O-GlcNAcylation could be a potential therapeutic approach for the treatment of sepsis." (PMID 37962578, 2024). "The caspase-11/GSDMD pathway contributes to NETs release and organ dysfunction in sepsis." (PMID 38169726, 2024).
Sepsis (continued). "However, recent studies have demonstrated that deficiency of RIPK3 or gasdermin D (GSDMD) can protect against TNF-induced SIRS, CLP-induced sepsis, or lipopolysaccharide (LPS)-induced septic shock." (PMID 38684668, 2024). "This implies that in addition to regulating NETs, GSDMD may be involved in sepsis through other mechanisms." (PMID 38584157, 2024). "Therefore, inhibition of GSDMD or Drp1 attenuated sepsis-induced neuronal damage in the hippocampus." (PMID 38627764, 2024). "By targeting Arg7 residues, GI-Y1 inhibits the interaction between PM and GSDMD-NT and decreases the secretion of inflammatory cytokines, thereby increasing the sepsis survival rate and providing protection against myocardial I/R injury and cardiac remodeling in mice." (PMID 38584157, 2024). "Modulating the activity of GSDMD or the complement system could help control the inflammatory response and reduce the severity of sepsis." (PMID 39445002, 2024). "Furthermore, platelets, which significantly contribute to DIC, have recently been shown to undergo GSDMD-induced pyroptosis, exacerbating the formation of NETs and inflammation during sepsis." (PMID 38584157, 2024). "Additionally, pharmacological inhibition of the NLRP3-caspase-1 inflammasome has demonstrated a reduction in the expression of both GSDMD and its cleavage form, GSDMD-N, effectively mitigating pyroptosis in the mouse brain following sepsis." (PMID 38627764, 2024). "GSDMB can also contribute to the development of sepsis by activating GSDMD." (PMID 38022612, 2023). "Conversely, inhibition of GSDMD could prevent inflammatory cell death and sepsis, as has been demonstrated in the case of necrosulfonamide, a direct chemical inhibitor of this gasdermin." (PMID 37627547, 2023). "Additionally, we highlight important targets involved in sepsis‐related regulatory mechanisms, including GSDMD, HMGB1, STING, and SQSTM1, among others." (PMID 38020710, 2023). "In particular, the activation of GsdmD-NT pores has previously been shown to mediate cytokine release that sustains and propagates proinflammatory signaling in the retina in a way that is similar to a “cytokine storm” during sepsis or viral infection." (PMID 37998361, 2023). "In contrast, immune-mediated diseases which are augmented by GSDMD activity such as sepsis and Familial Mediterranean Fever (FMF) may benefit from blockade of GSDMD-mediated pore formation." (PMID 37266429, 2023). "Hence, disulfiram, which is clinically utilized to treat alcoholism, inhibits GSDMD activation and shields mice in the lethal LPS-induced sepsis model." (PMID 36839481, 2023). "Necroptosis is another fundamental programmed cell death and is found in the universal biological conditions of development, inflammation, and cancer, and pyroptosis is a Gasdermin D (GSDMD)-mediated PCD that is implicated in inflammation, immunity, and sepsis and other diseases." (PMID 37325669, 2023). "Whether circulating GSDMD-p20 protein, as found in sepsis, is beneficial or detrimental to organ function, perhaps by acting as a danger signal (DAMP), requires further investigation." (PMID 38106412, 2023). "In addition, in vivo evidence proved that neutrophils expressed less GSDMD in Elacre-PD-L1flox mice than in Elacre-PD-L1WT mice under sepsis." (PMID 37056920, 2023). "Furthermore, in a mouse sepsis model, inhibition of GSDMD palmitoylation alleviated organ injury and extended the survival of septic mice." (PMID 37275856, 2023). "Numerous studies have revealed the relationship between abnormal GSDMD activation and various inflammatory diseases, including sepsis, coronavirus disease 2019 (COVID-19), neurodegenerative diseases, nonalcoholic steatohepatitis (NASH), inflammatory bowel disease (IBD), and malignant tumors." (PMID 37275856, 2023). "In neutrophils, GSDMD-NT is transported to azurophilic granules and autophagosomes, releasing IL-1β through autophagy-dependent pathways, which provide the rationale for neutrophil hyperactivation in sepsis." (PMID 38022612, 2023).
Sepsis (continued). "In this study, we have explored the regulation of non-canonical inflammasome constituents CASP4, CASP5 and GSDMD during sepsis and acute-on-chronic liver failure (ACLF)-associated immunosuppression." (PMID 38106412, 2023). "LPS-induced sepsis is predominantly associated with noncanonical inflammasome activation, and deficiency of caspase-11 or GSDMD protects from sepsis-induced death." (PMID 37275856, 2023). "Many studies have shown that GSDMD may promote the progression of sepsis by inducing pyroptosis and releasing inflammatory mediators." (PMID 38022612, 2023). "This suggests that the blockade of the GSDMD-related pyroptotic pathway could be a potential therapeutic for sepsis." (PMID 37275856, 2023). "GSDMD is regarded as a novel ideal target for sepsis treatment." (PMID 38022612, 2023). "Together, these results suggested that PD-L1 might interact with p-Y705-Stat3 to facilitate the translocation of PD-L1/p-Y705-Stat3 complex and initiate the transcription of GSDMD mRNA in neutrophils during sepsis." (PMID 37056920, 2023). "GSDMD, a pore-forming protein, plays a crucial role in the release of NETs in sepsis." (PMID 36467039, 2022). "Sepsis-related mortality induced by endotoxemia is largely due to caspase-11 activation, which can cleave GSDMD to unleash active membrane pore-forming peptides." (PMID 36189354, 2022). "It has been reported that inactivation of NLRP3 inflammasomes and inhibition of caspase-1-mediated cleavage of GSDMD could prevent pyroptosis in LPS-induced sepsis in a mouse model, thereby alleviating the septic shock." (PMID 35508474, 2022). "To further determine whether XBJ alleviated sepsis-induced NETs formation through the GSDMD signaling pathway, we used the GSDMD inhibitor, disulfiram (DIS) to block its expression in CLP mice and neutrophils." (PMID 36467039, 2022). "The western blot showed that CLP-induced sepsis promoted GSDMD, caspase-1, and NLRP3 expression." (PMID 35979014, 2022). "In sepsis, the main proteins in neutrophil pyroptosis (caspase-1/11, GSDMD) play a crucial role." (PMID 36059483, 2022). "Hu identified a potent inhibitor of GSDMD pore formation and protected against sepsis." (PMID 36419831, 2022). "Previous studies have shown that monocyte-derived plasma EV containing gasdermin D and activated caspase-1 are more abundant in patients with sepsis-related ARDS compared with healthy controls; uptake of these EV can induce human pulmonary vascular endothelial cell death." (PMID 35234046, 2022). "Neutrophil elastase could cleave GSDMD and cause neutrophil death, and the level of ELANE was reported to be associated with the severity of sepsis." (PMID 36618365, 2022). "However, the regulatory mechanism that controls GSDMD and influences inflammatory pyroptosis in sepsis-induced liver injury remains largely unclear." (PMID 35979014, 2022). "Interestingly, disulfiram still allows IL-1β and GSDMD processing, but abrogates pore formation, thus preventing IL-1β release and pyroptosis in LPS-induced sepsis." (PMID 36131917, 2022). "This study investigated the circRNA expression in liver tissues that underwent sepsis-induced damage to detect their roles in GSDMD regulation during sepsis and to determine if the altered circRNA expression could lead to therapeutic targets." (PMID 35979014, 2022). "Similarly, we observed that the inhibition of GSDMD by disulfiram in the sepsis model efficiently abrogates NETosis, systemic inflammation, and vital organs dysfunction, improving mice survival." (PMID 35799268, 2022). "In addition, the activation of the IL-17signaling pathway augments pyroptosis with GSDMD cleave and IL-1 1β and IL-18 release in pneumonia-induced sepsis." (PMID 36457716, 2022). "Syringaresinol ameliorated sepsis-induced cardiac dysfunction via the ER/SIRT1/NLRP3/GSDMD pathway." (PMID 35509275, 2022).
Sepsis (continued). "In a mouse model of sepsis, it was found that heparin intervention could minimize IL-1α and IL-1β release, as well as GSDMD distributions in the lungs after LPS stimulation." (PMID 36189354, 2022). "Furthermore, an RFWK motif-based peptide inhibitor can inhibit caspase-1/11 activation and its downstream substrates GSDMD and interleukin-1β cleavage, as well as lipopolysaccharide-induced sepsis in mice." (PMID 36322773, 2022). "GSDMD could mediate LPS-induced septic myocardial dysfunction and drive tissue injury in lethal polymicrobial sepsis." (PMID 36419831, 2022). "Collectively, these results demonstrate that GSDMD plays a key role in C. albicans infection and may represent a potential therapeutic target for C. albicans-induced sepsis." (PMID 34795266, 2021). "GSDMD disruption indeed protects against lethal bacterial sepsis, and Gsdmd-deficient mice show significantly improved survival compared to WT mice in both LPS-induced and cecal ligation and puncture (CLP) sepsis models." (PMID 34795266, 2021). "In addition, loss of GSDMD was shown to prevent tissues from damage in disease models of EAE, NOMID, IBD, sepsis, and FMF." (PMID 34784954, 2021). "This study demonstrates key functions for GSDMD in Candida’s escape from host immunity in vitro and in vivo and suggests that GSDMD may be a potential therapeutic target in C. albicans-induced sepsis." (PMID 34795266, 2021). "However, the physiological function of GSDMD in response to fungal pathogens and fungal-induced sepsis remains elusive." (PMID 34795266, 2021). "In summary, this study demonstrates key functions for GSDMD in host defense again Candida infection and suggests that GSDMD may be a potential therapeutic target in C. albicans-induced sepsis." (PMID 34795266, 2021). "There is also evidence that intraperitoneal injection of necrosulfonamide, an inhibitor of the necroptosis effector mixed lineage kinase domain like pseudokinase, acts as a chemical inhibitor of GSDMD, thereby protecting mice from LPS-induced sepsis compared to controls." (PMID 34858408, 2021). "Therefore, it is particularly important to explore the regulatory mechanisms of GSDMD in TEC pyroptosis during sepsis-related AKI." (PMID 34012408, 2021). "GPX4 was found to negatively regulate Gasdermin D-mediated pyroptosis in lethal polymicrobial sepsis by reducing lipid peroxidation; in contrast, conditional GPX4 knockdown in myeloid cells triggers macrophage pyroptosis with caspase-1/caspase-11-GSDMD-phospholipase C gamma 1 axis." (PMID 34899864, 2021). "A series of studies have shown that deficiency of caspase-11 and GSDMD protects against lethal endotoxemia and prevents DIC in sepsis." (PMID 34093202, 2021). "In summary, our data suggest that GSDMD plays a vital role in the pathophysiology of LPS-induced myocardial dysfunction and may be a crucial target for the prevention and treatment of sepsis-induced myocardial dysfunction." (PMID 34820388, 2021). "In myeloid cells, RIPK3-mediated necroptosis and GSDMD-mediated pyrolysis work together during the process of sepsis and may synergistically enhance tissue inflammation and damage." (PMID 34926535, 2021). "And it was found that estrogen administration could dramatically reverse sepsis-induced up-regulation of cleaved GSDMD and caspase-1 as well as NLRP3." (PMID 33002070, 2020). "The role of GSDMD in pyroptosis is to trigger lethal sepsis and septic shock." (PMID 31189875, 2019). "Interestingly, lipid peroxidation drives gasdermin D-mediated pyroptosis in lethal polymicrobial sepsis." (PMID 31060306, 2019). "In order to verify whether the role of hepatic GSDMD in sepsis depended on its cell membrane pore formation, we established the in vitro cell pyroptosis model in mouse primary hepatocytes (1 μg mL−1 LPS treatment for 6 h and then 20 μm Nigericin stimulation for 1.5 h)." (PMID 40856013, 2025).